TMX3 (thioredoxin related transmembrane protein 3)
Description:
Probable disulfide isomerase, which participates in the folding of proteins containing disulfide bonds. May act as a dithiol oxidase. Acts as a regulator of endoplasmic reticulum-mitochondria contact sites via its ability to regulate redox signals.
Synonyms: KIAA1830; TXNDC10; FLJ20793; PDIA13
Tractability: Antibody: its Gene Ontology location is reachable by antibodies, with high confidence; UniProt predicts a signal peptide or a membrane-spanning region. PROTAC: ubiquitination databases record sites on it; its protein half-life has been measured.
Gene: Protein-coding gene on chromosome 18 (68,673,688 to 68,715,147, reverse strand). Ensembl gene ENSG00000166479.
Subcellular location: Endoplasmic reticulum membrane
Pathways (Reactome):
Hemostasis: Platelet degranulation
Gene Ontology:
Molecular function: protein binding; protein disulfide isomerase activity; protein-disulfide reductase activity
Cellular component: cell surface; endoplasmic reticulum membrane; endoplasmic reticulum; plasma membrane; platelet alpha granule membrane
Genetic constraint (gnomAD): Loss-of-function variants: 13 observed, 30.15 expected, observed/expected ratio (o/e) 0.43, 90% interval 0.28 to 0.69. The upper end of that interval is the gene's LOEUF score, 0.69, which puts it in group 2 of 6, group 1 being the genes least tolerant of losing a copy. Missense variants: 310 observed, 334.17 expected, observed/expected ratio (o/e) 0.93, 90% interval 0.85 to 1.02. Synonymous variants: 120 observed, 109.53 expected, observed/expected ratio (o/e) 1.1, 90% interval 0.94 to 1.27.
Homologues: Orthologues: chimpanzee TMX3 (99% identical), macaque TMX3 (98% identical), rabbit TMX3 (93% identical), dog TMX3 (92% identical), pig TMX3 (92% identical), rat Tmx3 (92% identical), mouse Tmx3 (91% identical), guinea pig TMX3 (90% identical), tropical clawed frog tmx3 (67% identical), zebrafish tmx3a (47% identical), Caenorhabditis elegans ZK973.11 (23% identical), Drosophila melanogaster Tmx3 (23% identical), and 7 more. Paralogues in human: PDIA4 (20% identical), P4HB (19% identical), PDIA2 (19% identical), PDIA3 (19% identical), TXNDC5 (17% identical), PDILT (16% identical), PDIA5 (15% identical), ERP44 (14% identical), PDIA6 (14% identical), TXNDC11 (12% identical), ERP27 (10% identical), TMX1 (10% identical), and 1 more.
Diseases named in the same sentence as TMX3 in open-access papers:
TMX3 is named in the same sentence as 13 diseases in open-access papers, as found by Europe PMC text mining. Sharing a sentence is not in itself a finding about the gene and the disease. The quoted sentences say what the papers report.
microphthalmia (4 papers, 2010 to 2024). Congenital or developmental anomaly in which the eyeballs are abnormally small. "Our results show that haploinsufficiency for TMX3 results in a small eye phenotype and represents a novel genetic cause of microphthalmia and coloboma." (PMID 20485507, 2010). "Our data support a role for one of the deleted genes, TMX3, in eye development, as deficiency of this gene in humans and in zebrafish causes microphthalmia." (PMID 20485507, 2010). "A study identified 3 human patients with unilateral microphthalmia caused by germline TMX3 variants and postulated that the asymmetry was due to a delay in eye formation and that reduced gene dosage could be compensated for by different genes." (PMID 35034853, 2022). "We hypothesize that a deficiency of TMX3 predisposes to microphthalmia, and that further study of this gene and other thioredoxins in eye development is warranted." (PMID 20485507, 2010). "Based on our data, we propose that deficiency for TMX3 causes a small eye phenotype and may be involved in the pathogenesis of human microphthalmia in three known cases." (PMID 20485507, 2010). "The TMX3 [OMIM#616102] gene, localized on chromosome 18q22.1, has been reported to be associated with microphthalmia." (PMID 38711916, 2024). "Our in-situ studies enabled us to prioritize our candidate genes for anophthalmia and microphthalmia, with Tmx3 becoming the strongest candidate based on the intensity of expression and the duration of expression in the developing eye." (PMID 20485507, 2010). "Our expression studies lead us to re-sequence TMX3 in 162 patients with microphthalmia or anophthalmia." (PMID 20485507, 2010). "Interestingly, the microphthalmia phenotype was unilateral in all of the three human patients with TMX3 sequence alterations, whereas we found a bilateral reduction in eye size in fish." (PMID 20485507, 2010). "We chose to concentrate on the retinal phenotype in the morphants, and have not studied lens formation in the morphants, despite the expression of TMX3 in the lens epithelium, but it is possible that there is also a contribution to the microphthalmia from abnormal lens formation in the morphants." (PMID 20485507, 2010). "Sequence Alterations in TMX3 in 162 patients with Anophthalmia or Microphthalmia." (PMID 20485507, 2010). "Co-injection of human wild type TMX3 mRNA rescued the small eye phenotype obtained with both morpholinos, whereas co-injection of human TMX3(p.Arg39Gln) mutant mRNA, analogous to the mutation in the patient with microphthalmia and coloboma, did not rescue the small eye phenotype." (PMID 20485507, 2010). "Frequency of Microphthalmia and/or Coloboma with 6 ng MO1 Morpholino and 100 pg human TMX3 wild type or 100 pg of human TMX3/(p.Arg39Gln)." (PMID 20485507, 2010).
breast carcinoma (1 paper, 2012). "In general, more aggressive breast cancers (MDA-MB-231, SUM159PT, BCCL2, BCCL3) had lower levels of TMX1 and SOD1 relative to the luminal MCF-7 cells, and showed up-regulated expression of TMX3, Foxo1, GSS and SOD2." (PMID 22479642, 2012).
cancer (1 paper, 2023). A tumor composed of atypical neoplastic, often pleomorphic cells that invade other tissues. "TMX3 expression was decreased in 3 cancer types and significantly upregulated in 2 cancer types." (PMID 38147024, 2023). "Overall, the highest expression of TMX2 and the lowest expression of TMX3 was found in pan-cancer." (PMID 38147024, 2023). "In this study, based on TCGA and GTEx databases, we analyzed the expression of TMX family (TMX1, TMX2, TMX3, and TMX4) genes in 23 different cancer types." (PMID 38147024, 2023). "By estimating StromalScore and ImmuneScore in TME, we found that TMX1, TMX3, and TMX4 exhibited a positive correlation with StromalScore and StromalScore in most cancer types, while TMX2 expression was negatively correlated with StromalScore and ImmuneScore." (PMID 38147024, 2023).
TMX3 also shares sentences with these, for which no sentence is quoted: glioma (2 papers); Huntington disease (2); tumor (2); Anophthalmia (1); Atrophy (1); coloboma (1); coronary artery disease (1); diaphragmatic hernia (1); Micrognathia (1); Retinal coloboma (1).